ABL1 (ABL proto-oncogene 1, non-receptor tyrosine kinase)
Diseases named in the same sentence as ABL1 in open-access papers (continued):
Sharing a sentence is not in itself a finding about the gene and the disease.
leukemia (continued). "Immunoprecipitation results showed that FAM168A interacts with breakpoint cluster region (BCR) -Abelson murine leukemia (ABL1) fusion protein and AKT1, respectively." (PMID 31291942, 2019). "Another subset of Ph-like leukemia have ‘ABL class’ fusions involving ABL1, ABL2, CSF1R, and PDGFRB that are amenable to SRC/ABL tyrosine kinase inhibitors (TKIs) such as imatinib and dasatinib." (PMID 29464092, 2018). "Abl1 was initially thought to be the oncogene vital for the generation of leukemia’s triggered by the Abelson murine leukemia virus." (PMID 29455667, 2018). "Similar to other genes involved in leukaemia, ABL1 is involved in haematopoiesis and B-lymphoid development." (PMID 28819864, 2018). "This is not surprising since these patients have acquired mutations during the course of the disease (EGFR T790 M) and the fact that this dataset includes fusions (ROS1, ALK in lung cancer, ABL1 in leukemia)." (PMID 29544535, 2018). "In BCR/ABL1+ leukaemia, PAK1 and PAK2 are upstream regulators of the transcription factor STAT5 – a key node for initiation and maintenance of disease." (PMID 28707321, 2017). "ABL1 was first identified as an oncogene required for the development of human leukemia initiated by retroviruses or chromosome translocations." (PMID 27086914, 2016). "In this study, VS methods were applied to test their ability to identify inhibitors of leukemia target kinase ABL1 and its drug-resistant mutant form T315I." (PMID 23746052, 2013). "In this study, we have taken a retrospective approach to evaluate virtual screening methods for the leukemia target kinase ABL1 and its drug-resistant mutant ABL1-T315I." (PMID 23746052, 2013). "Ableson (ABL1), a control gene commonly used for leukemia samples, yielded a slightly lower CV in the combined TCGA data set (39.8%), but had a high MFC (26.9)." (PMID 24069164, 2013). "qRT-PCR was performed for each of the 14 new genes, as well as for 5 standard control genes (GAPDH, ACTB, TBP, HPRT1, ABL1), on cDNA from a panel of 14 leukemia samples (10 AML, 4 ALL) plus one CD34+ cord blood sample (using equal amounts of RNA)." (PMID 24069164, 2013). "The most specific leukemia antigens are peptides from aberrant proteins created by mutations or translocations only present in leukemia cells, such as the BCR/ABL1 tyrosine kinase in CML." (PMID 24427158, 2013). "Many of these candidates also corresponded to known gene fusions, including EWSR1/FLI1 in Ewing sarcoma and ABL1 rearrangements in several leukemia samples." (PMID 23637631, 2013). "In this study, we examine VS approaches for the leukemia target receptor ABL1, a protein tyrosine kinase now well characterized by knowledge of multiple inhibitors and target conformations." (PMID 23746052, 2013). "Although Abl1 and Abl2 are well known for driving leukemia development, their role in solid tumors has been appreciated only recently." (PMID 24223753, 2013). "Several studies have reported the presence of leukemia-lymphoma-associated fusion genes (e.g., BCR/ABL1, IGH/BCL2, TCRβ/γ) in normal individuals." (PMID 21637673, 2009). "Targeting ABL1 has been effective for leukemia, but its application for other cancers is limited." (PMID 40918650, 2025). "To understand whether OSM is functionally relevant for the disease progression of leukemia, we used Osm-deficient mice or WT mice as BM donors in models of FLT3-ITD- and BCR::ABL1-positive leukemia." (PMID 41372120, 2025). "Although best known for its fusion with ABL1 in leukaemia, recent studies suggest that BCR overexpression may also promote breast tumour progression through modulation of MAPK signalling pathways." (PMID 40813389, 2025).
leukemia (continued). "Using mouse models and human leukemia cell lines, the scientists demonstrated that ABL1 kinase may act as a tumor suppressor in these cancers by regulating cell proliferation, apoptosis, and differentiation." (PMID 40584293, 2025). "Several reports indicate that inhibition of autophagy may be a promising approach for the treatment of BCR::ABL1-mediated leukemia." (PMID 40113750, 2025). "Identification of the BCR::ABL1 transcript in CML entailed the discovery of molecular alterations as point mutations, fusion proteins and splice variants in other BCR::ABL1-negative leukemias." (PMID 39104388, 2024). "However, resistance to ABL TKIs can develop in CML patients due to BCR::ABL1 point mutations and CML leukemia stem cell (LSC)." (PMID 38714583, 2024). "In a previous study, ABL proto-oncogene 1, non-receptor tyrosine kinase (ABL1) located on chromosome 9 was found to fuse with multiple genes which are associated with leukemia." (PMID 37731134, 2023). "However, previous Ph+ leukemia models were unable to generate reciprocal ABL1::BCR fusion in combination with BCR::ABL1 fusion." (PMID 35999358, 2023). "Furthermore, it has recently been observed that the remaining genomic fragments were imperfectly reassembled, generating random fusions while maintaining the leukemia-initiating BCR::ABL1 fusion." (PMID 37296693, 2023). "Treatment and understanding of BCR::ABL1-positive leukaemias is a precision medicine success story." (PMID 38550948, 2023). "We and others reported that AML1-ETO caused “BRCAness” phenotype in leukemia cells, but loss of ABL1 expression did not sensitized leukemia cells to PARPi olaparib and RAD52i 6-hydroxy-DL-Dopa (PARPi and RAD52i)." (PMID 36959186, 2023). "Our work shows that a comprehensive molecular analysis might be necessary to characterize leukemias more likely to correspond to AMLs with the BCR::ABL1 WHO (World Health Organization) entity." (PMID 37895120, 2023). "In summary, ABL1 loss may serve as important diagnostic factor predicting more malignant phenotype of AML1-ETO and NUP98-fusions -positive leukemias as well as their unique pharmaceutical vulnerabilities to PI3K, ATR and DNA-PK inhibition." (PMID 36959186, 2023). "Thus, mimicking the initiation process of translocation, we induced CRISPR/Cas9-mediated DSBs simultaneously at the breakpoints of the BCR and ABL1 genes in a granulocyte-macrophage colony-stimulating factor (GM-CSF) dependent human leukemia cell line." (PMID 35999358, 2023). "However, tyrosine kinase inhibitors (TKIs) compete with ATP for binding to the active site, inhibiting the BCR::ABL1 activation and preventing leukaemia." (PMID 35884363, 2022). "ABL1 was initially identified as a driver of leukemia in mice and humans." (PMID 34022881, 2021). "Here we investigated the therapeutic potential of crizotinib, a TKI approved for targeting ALK and ROS1 in non-small cell lung cancer patients, which inhibited also the ABL1 kinase in cell-free systems, for the treatment of advanced and therapy-resistant Ph+ leukemia." (PMID 34110462, 2021). "ABL1 was first discovered as the oncogene in the Abelson murine leukemia virus in the last 38 years and was later recognized as an oncogene participating in chromosomal translocations in human leukemia." (PMID 34604069, 2021). "Both NF-κB and STAT3 are proven to be downstream targets of ABL1 in leukemia." (PMID 31396300, 2019). "Several inhibitors of c‐Abl (ABL1, Abelson tyrosine kinase), which is a member of the Abl family of nonreceptor tyrosine kinases, are currently approved as treatments for various forms of leukemia." (PMID 29704272, 2018). "B-LBL tumor cells are virtually always positive for B-cell markers CD19, CD79a, and CD22, and may be associated with the presence of leukemia rearrangements such as those involving ETV6, MLL, or ABL1." (PMID 30201877, 2018).
leukemia (continued). "Similarly, deleting the remaining normal copy of ABL1 in BCR-ABL1+ murine leukemia stem cells led to more aggressive disease, enhanced proliferation, inhibition of genotoxic stress-induced apoptosis and increased chromosomal aberrations." (PMID 27965460, 2017). "Here, we studied the individual roles of PAK1 and PAK2 in BCR/ABL1+ leukaemia." (PMID 28707321, 2017). "It is well known that the ABL1 kinase has altered catalytic specificity in human leukemia." (PMID 27570624, 2016). "Point mutations in the ABL1 kinase domain are an important mechanism of resistance to tyrosine kinase inhibitors (TKI) in BCR-ABL1-positive and, as recently shown, BCR-ABL1-like leukemias." (PMID 27801667, 2016). "However, the control genes identified here all proved to be more consistent than ABL1 both by RNA-seq and qRT-PCR of leukemia samples, making them ideal candidates for use in MRD." (PMID 24069164, 2013). "Additionally, the presence of the BCR::ABL1 fusion supports the classification of this leukemia as MPAL (T/myeloid) with a defined genetic abnormality, in accordance with the World Health Organization (WHO), fifth edition, and the International Consensus Classification (ICC)." (PMID 40605863, 2025). "Studies regarding TKI resistance in leukemia have mostly centered on cancer genetic alterations, for example, acquired mutations (which happen in about 1/3 of progressive cases) in the kinase domains of BCR::ABL1 that reduce or even fully impair TKIs’ binding to ABL kinase." (PMID 41203598, 2025). "With the proviso you have a sensitive and specific assay, cell-free detection of ctDNA in solid cancers might be less susceptible to Poisson noise than other MRD-testing assays that rely on presence of intact cancer cells in a sample (e.g. detection of BCR::ABL1 transcripts in leukaemia cells)." (PMID 38637690, 2024). "In addition, ABL1 kinase phosphorylates and regulates the activity of two DNA repair enzymes, PARP1 and RAD52, inhibition of which triggered synthetic lethality in BRCA1/2-deficient leukemia cells." (PMID 36959186, 2023). "In addition, RNA-seq analyses revealed broad spectrum of ABL1 expression in various leukemias." (PMID 36959186, 2023). "This table shows the BCR::ABL1-independent pathways and their inhibitors that could be used in combination with TKIs, and the stage of their current development for diseases listed that could be repurposed in the treatment of Ph+ leukaemias." (PMID 35884363, 2022). "Again, three recipients from each group were sacrificed on day 25, which revealed that the BCR/ABL1-Rora group recipients had a smaller gross splenic appearance with a significantly lower weight and significantly lower percentage and total number of leukemia cells." (PMID 35414788, 2022). "Therefore, the leukemia cell line is a primary choice for ABL1-targeted therapy." (PMID 32110969, 2020). "We report that malignant transformation and transcriptional reprogramming by BCR::ABL1 is indeed defined by enhancer reprogramming and that enhancer signatures differentiate Ph+B-ALL from other leukemias." (PMID 41764406, 2026). "A parallel network, consisting of Wnt-JUP-MYC-BIRC5 axis, operates in BCR::ABL1-positive B-cell ALL, where JUP acts as a key driver required for leukemia maintenance." (PMID 41596324, 2026). "In B-ALL, we find that subpopulation dynamics are useful to predict BCR::ABL1 status and post-induction MRD (threshold frequency of 10−3 leukemia cells detected using specialized flow cytometry)." (PMID 41295979, 2026). "Our analysis suggests the existence of dedifferentiating transitions to a CD34+/CD38− stem cell–like immunophenotype in leukemia samples collected from patients with B-ALL, and the tendency for these transitions is especially strong in B-ALL with BCR::ABL1." (PMID 41295979, 2026).
leukemia (continued). "In a recent study using a murine Arf−/−Bcr-Abl1 mouse model, BCR::ABL1-specific CD4+ memory T cells played a protective role, with T cell depletion drastically increasing leukemia outgrowth after dasatinib or cytotoxic chemotherapy." (PMID 40503229, 2025). "Asciminib, an allosteric inhibitor used to treat BCR::ABL1+ leukemias, has demonstrated in vitro and in vivo efficacy for NUP214::ABL1 ALL as long as the ABL1 SH3 domain is present, supporting use of asciminib in NUP214::ABL1 ALL." (PMID 40247105, 2025). "A recent study by Golovine et al47 has highlighted the significant role of ABL1 kinase in AML1-ETO and NUP98 (nucleoporin 98)-PMX1 (paired related homeobox 1) leukemias." (PMID 40584293, 2025). "For example, our prior work showed that CD9 activates the PI3K/Akt pathway to drive leukemia progression and chemoresistance in BCR::ABL1+ cells." (PMID 38001171, 2024). "Consequently, testing for mutated BCR::ABL1 transcripts may not identify all resistant leukaemia cells." (PMID 38637690, 2024). "A DEK::NUP214 fusion was identified in five leukemias (cases 1-5), whereas SET::NUP214 and NUP214::ABL1 were found in two cases each (cases 6 and 7, and 8 and 9, respectively)." (PMID 38571499, 2024). "Abl1 kinase inhibitors have been approved for their clinical relevance in many tumor types, including leukemia and HCC, in patients showing the overexpression and/or activation of Abl1." (PMID 39123481, 2024). "Dasatinib is a drug developed for the treatment of leukemias, and it exerts its antitumoral activity by inhibition of SCR/ABL1 kinases, and by inhibiting the BCL-ABL1 fusion protein, the driving oncogene of chronic myeloid leukemia." (PMID 38491064, 2024). "ALK fusions were predominantly observed in lung cancer and lymphoma, while RET, ABL1, and BRAF fusions have been identified most frequently in thyroid cancer, leukemias, and pediatric low-grade gliomas, respectively." (PMID 38877018, 2024). "The patient-derived xenograft (PDX) mice succumbed to their leukemia at a median of 76 and 78 days (p = 0.0207 and p = 0.0295, respectively, compared with the BCR::ABL1 control with a median survival of 278 days)." (PMID 37483494, 2023). "The tyrosine kinase activity of the BCR::ABL1 protein is dysregulated, and primitive hematopoietic cellular homeostasis systems are changed by BCR::ABL1, which also increases leukemia cell proliferation." (PMID 37670241, 2023). "Overall survival of patients with leukemias in the context of ABL1 expression levels revealed that chronic lymphocytic leukemia (CLL) and AML displaying low levels of ABL1 mRNA expression had shorter overall survival, while opposite effect was detected in ALL." (PMID 36959186, 2023). "FDA-approved drugs targeting ABL1/2 have been utilized for decades to treat leukemias driven by activated forms of ABL1 (e.g., BCR-ABL)); therefore, repurposing these agents for treatment-refractory melanomas would be an attractive treatment strategy." (PMID 36765910, 2023). "Since our initial analysis detected ABL1 deletions in leukemias carrying AML1-ETO and NUP98 translocations, we investigated the role of ABL1 in these leukemias." (PMID 36959186, 2023). "We reported that stimulation of the normal ABL1 kinase by a chemical compound DPH enhanced anti-leukemia effect of TKIs such as imatinib and ponatinib in human and murine leukemias expressing BCR-ABL1, TEL-ABL1 and NUP214-ABL1." (PMID 36959186, 2023). "Of patients with MRD+ or relapsed leukemia after HCT, 84% were positive for at least one TAA/ABL1 in the peripheral blood." (PMID 36248870, 2022). "While more paired samples are needed to demonstrate accuracy as a leukemia surveillance tool, our ddPCR test showed sensitive changes in TAA/ABL1 ratios that matched clinical course even in low level leukemia disease over the course of treatment." (PMID 36248870, 2022).
leukemia (continued). "Confirming that our recipient mice indeed died of leukaemia, BCR::ABL1 transcripts were detectable in the peripheral blood of recipient mice but not controls (left)." (PMID 36536477, 2022). "When comparing the targets between Dasatinib and imatinib/nilotinib, there are six common target kinases: Kit, PDGFR, ABL1, DDR1, ARG (ABL2), and the fusion kinase present only in certain leukemias, BCR-Abl." (PMID 36338985, 2022). "BCR::ABL1-independent PI3K/AKT pathway activation and imatinib resistance was also observed in primary leukaemia cells and in imatinib-treated CML patients." (PMID 35884363, 2022). "Mechanistically, circBA9.3 strengthened the antiapoptotic properties of K562 cells and upregulated the levels of both ABL1 and BCR-ABL1 proteins to reduce the sensitivity of leukemia cells to TKIs, thereby promoting resistance against TKI therapy." (PMID 33069241, 2020). "Pharmacological targeting of BCR/ABL1 by imatinib and its successors have converted CML from a deadly disease to leukemia with very good prognosis." (PMID 33322186, 2020). "This protein is increased in cells expressing BRC/ABL1 fusion protein, and a cytosolic isoform of BIP has been described to activate PERK signaling and drive survival in leukemia cells." (PMID 26734574, 2015). "The target of ‘Dasatinib’ is ‘Tyrosine-protein kinase ABL1’ (ABL1: BCRABL), the disease gene of ‘Leukemia, Acute Myeloid; Aml’ is ‘Mast/stem cell growth factor receptor Kit’ (KIT)." (PMID 24244318, 2013). "Disruption of autoinhibition, such as by translocation of Abl1 or Abl2 next to a variety of different genes (e.g. Bcr, Tel, ETV6), leads to constitutive activation, which drives malignancies, particularly leukemias." (PMID 24223753, 2013). "For example in the pair (IGFI, IGFII) the genes are both members of the family of insulin-like growth factors, and in the pair (BCR, ABL1) the fusion of the BCR and ABL1 genes has been found to be a "recurrent aberration in B cell precursor leukemia cells"." (PMID 15847682, 2005). "Additionally, the persistence of leukemia stem cells (LSCs), which are inherently less dependent on BCR::ABL1 signaling and often quiescent, presents a key therapeutic challenge." (PMID 41510882, 2026). "In conclusion, this case underscores the clinical imperative of utilizing molecular diagnostics, particularly whole-transcriptome sequencing, in instances where conventional BCR::ABL1 assays yield negative results despite cytogenetic evidence of Ph+ leukemia." (PMID 41211450, 2025). "Although BCR::ABL1-positive B-ALL did not correlate with any specific marker (p = 0.34), all cases in this series exhibited at least one leukemia-associated immunophenotype (LAIP) suitable for MRD monitoring via flow cytometry." (PMID 40076750, 2025). "Notably, all of these genetic abnormalities can present as distinct single lineage leukemias (e.g., B-ALL with BCR::ABL1 fusion) but are classified as ALAL/MPAL based on meeting MPAL/ALAL immunophenotypic criteria." (PMID 40075717, 2025). "The adverse impact of CD9 was confined to specific cytogenetics, notably BCR::ABL1+ rather than KMT2A-rearranged leukemia." (PMID 38001171, 2024). "Finally, the detection of both NUP214::ABL1 and PCM1::FGFR1 fusions in the near ETP-ALL of case 8 leaves no information as to which fusion was the primary and which was secondary in this leukemia." (PMID 38571499, 2024). "Since a number of ABL1/2 and DDR1 inhibitors are FDA-approved for treating leukemia, these data may pave the way for testing their clinical efficacy in combination with MEK for treatment-refractory NRAS-driven melanomas." (PMID 36765910, 2023). "On the other hand, ABL1 kinase could become a therapeutic target since imatinib increased the sensitivity of AML1-ETO and NUP98-fusions -positive leukemias to PI3K, ATR and DNA-PK inhibitors." (PMID 36959186, 2023).